TYR (tyrosinase)
Description:
This is a copper-containing oxidase that functions in the formation of pigments such as melanins and other polyphenolic compounds. Catalyzes the initial and rate limiting step in the cascade of reactions leading to melanin production from tyrosine (By similarity). In addition to hydroxylating tyrosine to DOPA (3,4-dihydroxyphenylalanine), also catalyzes the oxidation of DOPA to DOPA-quinone, and possibly the oxidation of DHI (5,6-dihydroxyindole) to indole-5,6 quinone.
Synonyms: OCAIA; OCA1A; OCA1; ATN; CMM8; SHEP3
Tractability: Small molecule: an approved drug acts on it; a high-quality ligand is known; it belongs to a druggable protein family. Antibody: UniProt predicts a signal peptide or a membrane-spanning region. PROTAC: a small molecule that binds it is known.
Target class: Enzyme; Oxidoreductase
Gene: Protein-coding gene on chromosome 11 (89,177,875 to 89,295,759, forward strand). Ensembl gene ENSG00000077498.
Subcellular location: Melanosome membrane; Melanosome
Subcellular location (Human Protein Atlas): Vesicles
Pathways (Reactome):
Developmental Biology: Regulation of MITF-M-dependent genes involved in pigmentation
Metabolism: Melanin biosynthesis
Gene Ontology:
Molecular function: copper ion binding; identical protein binding; protein binding; tyrosinase activity; protein homodimerization activity; oxidoreductase activity
Biological process: melanin biosynthetic process; response to blue light; eye pigment biosynthetic process; melanin biosynthetic process from tyrosine; pigmentation; visual perception; developmental pigmentation; eye pigmentation; response to cAMP; response to UV; response to vitamin D
Cellular component: cytoplasm; perinuclear region of cytoplasm; Golgi-associated vesicle; lysosome; melanosome; melanosome membrane
Genetic constraint (gnomAD): Loss-of-function variants: 58 observed, 53.6 expected, observed/expected ratio (o/e) 1.08, 90% interval 0.88 to 1.35. The upper end of that interval is the gene's LOEUF score, 1.35, which puts it in group 5 of 6, group 1 being the genes least tolerant of losing a copy. Missense variants: 732 observed, 671.94 expected, observed/expected ratio (o/e) 1.09, 90% interval 1.02 to 1.16. Synonymous variants: 263 observed, 241.57 expected, observed/expected ratio (o/e) 1.09, 90% interval 0.98 to 1.21.
Gene-disease validity (ClinGen):
ClinGen rates the evidence that TYR causes each of these diseases.
oculocutaneous albinism type 1 (autosomal recessive): Definitive. Type 1 oculocutaneous albinism (OCA1) describes a group of tyrosine related OCAs that includes OCA1A, OCA1B, type 1 minimal pigment oculocutaneous albinism (OCA1-MP) and type 1 temperature sensitive oculocutaneous albinism (OCA1-TS).
Homologues: Orthologues: chimpanzee TYR (99% identical), macaque TYR (96% identical), pig TYR (90% identical), rabbit TYR (89% identical), dog TYR (89% identical), rat Tyr (87% identical), mouse Tyr (86% identical), guinea pig TYR (86% identical), tropical clawed frog tyr (68% identical), zebrafish tyr (61% identical), Caenorhabditis elegans tyr-2 (23% identical). Paralogues in human: TYRP1 (39% identical), DCT (38% identical).
Diseases named in the same sentence as TYR in open-access papers:
TYR is named in the same sentence as 271 diseases in open-access papers, as found by Europe PMC text mining. Sharing a sentence is not in itself a finding about the gene and the disease. The quoted sentences say what the papers report.
melanoma (1,092 papers, 1986 to 2026). A malignant, usually aggressive tumor composed of atypical, neoplastic melanocytes. "ER stress is caused by the over-synthesis of Tyrosinase, and we previously demonstrated that this occurs due to the treatment of the B16 melanoma cell line with α-MSH." (PMID 41516372, 2026). "TYR catalyzes the conversion of tyrosine to melanin; variants affecting this gene have been related to albinism and increased melanoma risk." (PMID 40869905, 2025). "N-phenylthiourea and d-penicillamine efficiently inhibited TYR activity and melanin synthesis in melanoma cells, which was associated with increased sensitivity to γ-irradiation." (PMID 39970778, 2025). "For the TYR variants (rs1042602–p.S192Y and rs1126809–p.R402Q), rs1042602 was associated with melanoma risk in both the codominant and recessive models (OR = 3.32, CI = 1.01–10.94, p = 0.032)." (PMID 40429816, 2025). "Shan Yang found that HCP antagonizes the effects induced by α‐MSH‐ and ET‐1 on MNT‐1 human melanoma cells; moreover, it promotes melanin transfer to keratinocytes, inhibits TYR activity, and reduces the levels of proteins associated with melanogenesis." (PMID 39128885, 2025). "In the current study, two types of alfalfa seed extract exerted significant melanin inhibition in mouse melanoma cells in association with decreased protein and mRNA levels of the melanogenesis‐related factors, tyrosinase, TRP1 and MITF." (PMID 40524653, 2025). "To evaluate the therapeutic efficacy of CD38i, we subcutaneously engrafted the YUMM1.7 mouse melanoma tumor, which carries human-relevant mutations (BrafV600E; Cdkn2a−/−; Pten−/−; Tyrosinase:CreERT2), in B6 mice." (PMID 40117361, 2025). "Previous reports have shown that up-regulated Tyr transcription is related to increased melanin production, while knockout of tyrosinase caused pigment loss in melanoma cells, zebrafishes, mice and rabbits." (PMID 40549156, 2025). "SNPs in another locus on chromosome 11, near genes GRM5 and TYR, have been associated with skin cancer, melanoma, skin sensitivity to sun, insomnia, tan response, sunburns and hearing loss." (PMID 39975919, 2025). "Higher expression of MLANA and TYR have also been linked to phenotype switching in melanoma and is associated with a more differentiated phenotype." (PMID 40075679, 2025). "Another study explored the use of a DNA vaccine encoding tyrosinase epitopes delivered intranodally in Stage IV melanoma patients." (PMID 40746887, 2025). "Mutations in the tyrosinase gene can lead to increased enzyme activity and melanin overproduction, consequently increasing the risk of melanoma development." (PMID 40332760, 2025). "This was associated with a reduction of TYR activity compared to non-α-syn-expressing cells, suggesting that during stressful conditions (e.g. melanoma-promoting events), α-syn negatively regulates the melanin synthesis response." (PMID 41460324, 2025). "Most primary melanoma tumors contain melanin because of the increased melanogenesis caused by overexpression of tyrosinase in melanoma cells." (PMID 40019914, 2025). "One of the most vital enzymes of the melanogenic metabolic pathway is tyrosinase, which is closely associated with malignant melanoma and many pigmentation disorders." (PMID 40722869, 2025). "This determination was initially made from a GWAS indicating that the rs1126809 variant of the tyrosinase gene TYR, which is involved in converting tyrosine to melanin, increased the risk of vitiligo and reduced the risk of melanoma." (PMID 39817457, 2025). "A combination of cancer testis antigens, MAGE-C2, MAGE-A3 and NY-ESO-1, and tumor-associated antigens, gp100 and tyrosinase, was chosen as they are known to be widely expressed on melanoma and are able to induce cytotoxic T cells that can lyse tumor cells." (PMID 38395969, 2024).
melanoma (continued). "For example, the Oncept melanoma vaccine—a DNA vaccine that is used to treat melanoma in canines—uses human-DNA-encoding tyrosinase to elicit an immune response in dogs; however, while the vaccine appears to be safe, its efficacy is limited." (PMID 38732242, 2024). "Including, ACTB as a hub protein associated with tyrosinase-mediated melanogenesis in melanoma cells." (PMID 38754850, 2024). "We further validated our findings in another immunotherapy-resistant tumor model, YUMM1.7, a mouse melanoma line containing human-relevant mutations (BrafV600E; Cdkn2a−/− Pten−/−; Tyrosinase:CreERT2)." (PMID 38451948, 2024). "YWHAZ has been identified as a connecting factor between tyrosinase-triggered melanin production and melanoma growth, highlighting its close association with melanin synthesis." (PMID 39125816, 2024). "The same TriMix-DC-MEL vaccine, based on mRNA coding for four melanoma-associated antigens (tyrosinase, gp100, MAGE-A3, and MAGE-C2), has been also combined with ipilimumab administration in 30 advanced melanoma patients." (PMID 36992220, 2023). "Inhibition of TRP-1 and TRP-2 activity as well as related transcription factor microphthalmia transcription factor (MITF) is implicated as the mechanism of tyrosinase reduction in B16F10 melanoma cells treated with ferulic acid." (PMID 36614303, 2023). "Early clinical trials for the treatment of melanoma patients describe the pulsing of in-vitro-generated DCs with either a cocktail of melanoma-associated peptides (tyrosinase, Melan-A/MART-1, gp100) or peptides derived from MAGE-1 and MAGE-3." (PMID 37569548, 2023). "The overactivity or overexpression of TYR can result in hyperpigmentation disorders and has been associated with melanomas." (PMID 37570734, 2023). "Excess melanin, resulting from abnormal overexpression of tyrosinase, is associated with hyperpigmentation and melanoma diseases." (PMID 36982292, 2023). "Participants were melanoma patients who demonstrated expression of melanoma-associated tumor antigen gp100 and tyrosinase." (PMID 36851271, 2023). "Direct intradermal administration of protamine-stabilized mRNA encoding for melanoma antigens (Melan-A, Tyrosinase, gp100, MAGE-A1, MAGE-A3, Survivin) to 21 metastatic melanoma patients was well-tolerated, inducing no adverse events of grade 3 or higher." (PMID 36992220, 2023). "Melan A, tyrosinase, and S100 are commonly used genes by pathologists to identify melanoma-associated proteins." (PMID 38260202, 2023). "In analyzing the clinical trial results, ex vivo ELISPOT assays were performed to detect IFNγ-producing CD8 and CD4 T-cell responses specific to the DC vaccine loaded melanoma-associated antigens Tyrosinase, MART-1 and MAGE-A6." (PMID 37938561, 2023). "HLA-A2.1 patients with uveal melanomas were injected with autologous DCs electroporated with mRNA encoding melanoma-associated antigens tyrosinase and/or gp100." (PMID 37834126, 2023). "DCs electroporated with mRNA encoding the melanoma-associated antigens tyrosinase or gp100 and TriMix and administered intranasally to patients with advanced melanoma evoked modest antitumor responses, according to the findings of one investigation." (PMID 37420174, 2023). "The knockdown of this gene causes reduced tyrosinase activity and low melanin content in human melanoma cell lines." (PMID 36683094, 2023). "This O-quinone is one of the precursors of melanin and, therefore, an overexpression of tyrosinase induces an overproduction of the pigment, which is associated with hyperpigmentation and melanoma diseases." (PMID 36982292, 2023). "Some of the identified lead SNPs, mapping IRF4, HERC2, and TYR, were also found to be associated with melanoma or other skin diseases in the UKBiobank." (PMID 36672889, 2023). "Tyrosinase is known to be a melanoma-associated antigen; consequently, its loss would be beneficial for tumor escape from the immune system." (PMID 36556369, 2022).
melanoma (continued). "At a concentration of 60 μg/mL, PP60 caused a significant decrease in melanin synthesis in the melanoma cells as well as inhibition of tyrosinase activity." (PMID 36091602, 2022). "The chemical agent NPrCAP has been shown to be a good substrate for tyrosinase and to be selectively incorporated into melanoma cells, causing cytotoxicity." (PMID 35742905, 2022). "The mutagen ethylmethanesulfonate can induce amelanotic variants that can be isolated from wild-type melanotic melanoma cells, and these amelanotic variants lost tyrosinase activity." (PMID 35265199, 2022). "The detection of melanoma-associated mRNAs (MAGE-3, MART-1 and tyrosinase) in CSF of stage IV melanoma patients was indicative of subsequent brain metastasis." (PMID 36704194, 2022). "The function of tyrosinase is regulated by a Microphthalmia-associated transcription factor or MITF that is an oncogene in the malignancy process of melanoma." (PMID 35656077, 2022). "The phenomenon of aging results in tyrosinase disorders and is considered the primary causative agent of melasma or freckles and malignant melanoma." (PMID 36387032, 2022). "We assessed the capacity of zDCs to induce Ag-specific CTL responses aimed at melanoma-associated peptides derived from proteins gp100, tyrosinase, and melan-A." (PMID 35269457, 2022). "NPrCAP is a good substrate for tyrosinase and is selectively incorporated into melanoma cells, which causes cytotoxicity in vitro and in vivo." (PMID 35742905, 2022). "MITF induces Bcl-2 expression, reducing tumorigenesis in human melanoma cells and increasing the tyrosinase expression associated with melanogenesis." (PMID 34067095, 2021). "Tyrosinase dysfunctions induce aging phenomenon and is the main causal agent of malignant melanoma and freckles or melissa like pigmentary disorders." (PMID 34098912, 2021). "The inhibitors of elastase are useful to overcome the loss of skin sagging and elasticity, while those of tyrosinase allow to limit melanin synthesis and, hence, ensure a breakdown of skin disorders, i.e., hyperpigmentation and melanoma." (PMID 34679706, 2021). "DCs were loaded directly with HLA-A*0201-restricted melanoma-associated peptides (gp100 and tyrosinase)." (PMID 34631558, 2021). "In human clinical trials on malignant melanoma patients, DNA vaccines encoding xenogeneic melanosomal antigens (tyrosinase, gp100) induced CD8( +) T-cell responses and epitope spreading of CD8 + T-cell response was observed." (PMID 33156394, 2021). "More interestingly, we found that low TYR expression displays a significant association with unfavorable prognosis in BRAF-mutated melanoma subtypes." (PMID 34199192, 2021). "Healthy human subjects develop spontaneous CD8+ T cell responses to melanoma associated antigens (MA) expressed by normal melanocytes, such as Tyrosinase, MAGE-A3, Melan/Mart-1, gp100, and NY-ESO-1." (PMID 33435427, 2021). "Previous pharmacological investigations have revealed that an abnormal level of TYR is tightly associated with various dermatoses, including albinism, age spots, and malignant melanoma." (PMID 34436092, 2021). "As a critical melanoma-associated antigen, TYR can be recognized by autologous T lymphocytes, thus inducing effective tumor-specific responses." (PMID 34436092, 2021). "Another case of malignant melanoma with loss of conventional melanocytic markers except Tyrosinase showed immunostaining in both the primary lesion and lymph node metastasis." (PMID 34449584, 2021). "Deleterious variants in TYR/OCA1 were more common in AHM melanoma cases than in PM cases and the same was true for the OCA2 hypomorphic allele p.V443I." (PMID 32966289, 2020). "Perillyl alcohol topical treatment showed the ability to delay development and incidence of DMBA-induced melanoma in transgenic mice harboring a mutated HaRas gene driven by the tyrosinase promoter (TPras)." (PMID 32948083, 2020).
melanoma (continued). "Although melanoma in albinism patients is rare, it is almost invariably presents as amelanotic melanoma as seen in TYR-mutated OCA1 patients." (PMID 32966289, 2020). "Cysteine mutation in tyrosinase, which is required for the production of melanin from tyrosine, is linked with albinism and melanoma." (PMID 32545905, 2020). "In considering the frequency of individual rare TYR variants in different subtypes of melanoma, the p.A23T variant showed the largest difference, occurring at a higher frequency in AHM vs PM (X2 unadjusted P = 0.008)." (PMID 32966289, 2020). "In a cohort of fifteen MM patients, autologous pDCs were activated and loaded with melanoma-associated peptides (gp100 and tyrosinase), and subsequently injected within the lymph node." (PMID 32054102, 2020). "As lighter skin color is recognized as a risk factor for melanoma this would provide a plausible explanation for the raised frequency of TYR and OCA2 p.V443I albinism/deleterious gene allele carriers in melanoma cases." (PMID 32966289, 2020). "In an early clinical phase I trial, stage IV melanoma patients were intranodally infused with pDNA encoding for melanoma-associated tyrosinase every two weeks for a total of four times." (PMID 32917034, 2020). "Rare deleterious variants in TYR/OCA1 were more common in amelanotic/hypomelanotic melanoma cases than pigmented melanoma cases (set mixed model association tests P = 0.0088)." (PMID 32966289, 2020). "Its presence results in the reduction of activity of tyrosinase, a key enzyme in of the melanin production pathway, and some authors reported an increased risk of melanoma in carriers." (PMID 33167923, 2020). "We excluded MITF p.E318K and TYR p.T373K from our analysis as they are associated with moderate-risk melanoma susceptibility." (PMID 33077847, 2020). "After the DC vaccines, 18 of 31 (58%) tested had developed increased T cell responses over baseline to vaccine-encoded melanoma antigens (Tyrosinase: 7 CD8+/4 CD4+; MART-1: 6 CD8+/7 CD4+; MAGE-A6: 4 CD8+/ 2 CD4+ responses across 18 pt)." (PMID 31014399, 2019). "Recently, the expression of the melanocyte-specific markers MITF, MLANA and TYR has been associated with a highly proliferative melanoma cell phenotype that metastasizes to multiple organs." (PMID 30053879, 2018). "Genes annotated to tyrosinase and syntenin-1, a melanoma differentiation-associated protein were found in the highly expressed gene set for Dendrophyllia sp." (PMID 28743941, 2017). "The role of RAS in melanoma development was investigated through the melanocyte-specific expression of mutated HRAS: tyrosinase-driven expression of HRasV12G in mouse melanocytes failed to induce melanoma development." (PMID 29156643, 2017). "Genetic silencing or chemical inhibition of NAT10 resulted in diminished melanin synthesis through the suppression of melanogenesis-stimulating genes such as those encoding dopachrome tautomerase (DCT) and tyrosinase in B16F10 melanoma cells." (PMID 28880216, 2017). "The licensing of Oncept, a xenogeneic DNA vaccine encoding human tyrosinase for the treatment of melanoma in dogs has led to its widespread use in veterinary oncology." (PMID 26871296, 2016). "Here, by testing a broad range of well-known melanoma associated antigens, we had evidences of immunological activation against tyrosinase, gp100 and NY-ESO-1 in the two patients showing long-term stable disease." (PMID 25933939, 2015). "The chemotherapeutic agent methotrexate (MTX) causes an increase in MITF and its direct target TYR (tyrosinase) that inhibit invasiveness in melanoma." (PMID 25763355, 2015). "NB-DNJ can effectively inhibit the cellular tyrosinase activity and results in an appreciable loss of pigmentation in the treated melanoma cells." (PMID 25254219, 2014).